H3C14 (H3 clustered histone 14)
Description:
Core component of nucleosome. Nucleosomes wrap and compact DNA into chromatin, limiting DNA accessibility to the cellular machineries which require DNA as a template. Histones thereby play a central role in transcription regulation, DNA repair, DNA replication and chromosomal stability. DNA accessibility is regulated via a complex set of post-translational modifications of histones, also called histone code, and nucleosome remodeling.
Synonyms: H3F2; H3FM; HIST2H3C; MGC9629; H3/m; H3; H3.2; H3FN
Gene: Protein-coding gene on chromosome 1 (149,840,687 to 149,841,208, reverse strand). Ensembl gene ENSG00000203811.
Subcellular location: Nucleus; Chromosome
Subcellular location (Human Protein Atlas): Nucleoplasm
Pathways (Reactome):
Gene expression (Transcription): B-WICH complex positively regulates rRNA expression; DNA methylation; ERCC6 (CSB) and EHMT2 (G9a) positively regulate rRNA expression; MLL4 and MLL3 complexes regulate expression of PPARG target genes in adipogenesis and hepatic steatosis; NoRC negatively regulates rRNA expression; PRC2 methylates histones and DNA; RNA Polymerase I Promoter Escape; RNA Polymerase I Promoter Opening; RUNX1 regulates genes involved in megakaryocyte differentiation and platelet function; RUNX1 regulates transcription of genes involved in differentiation of HSCs; Regulation of endogenous retroelements by KRAB-ZFP proteins; Regulation of endogenous retroelements by Piwi-interacting RNAs (piRNAs); Regulation of endogenous retroelements by the Human Silencing Hub (HUSH) complex; SIRT1 negatively regulates rRNA expression; Transcriptional regulation by small RNAs
Chromatin organization: CHD1 and CHD2 subfamily; CHD6, CHD7, CHD8, CHD9 subfamily; ChAHP complex assembly; Chromatin modifying enzymes; HATs acetylate histones; HDACs deacetylate histones; HDMs demethylate histones; Interaction of NuRD complexes with transcription factors; NuRD complex assembly; PKMTs methylate histone lysines; RMTs methylate histone arginines
Disease: Defective pyroptosis; Dengue Virus-Host Interactions; HCMV Early Events; HCMV Late Events
Signal Transduction: Activated PKN1 stimulates transcription of AR (androgen receptor) regulated genes KLK2 and KLK3; Estrogen-dependent gene expression; Formation of the beta-catenin:TCF transactivating complex; Pre-NOTCH Transcription and Translation
Developmental Biology: Activation of anterior HOX genes in hindbrain development during early embryogenesis; Chromatin modifications during the maternal to zygotic transition (MZT); Transcriptional regulation of granulopoiesis
Immune System: FXIIa activates plasma kallikrein-kinin system; Interleukin-7 signaling; Regulation of PD-L1(CD274) transcription
and 8 more pathways
Gene Ontology:
Molecular function: protein binding; nucleosomal DNA binding; structural constituent of chromatin; DNA binding; protein heterodimerization activity
Biological process: nucleosome assembly; chromatin organization; heterochromatin formation
Cellular component: extracellular exosome; nucleoplasm; nucleosome; nucleus; extracellular region; chromosome
Homologues: Orthologues: Drosophila melanogaster His3:CG33851 (100% identical), Drosophila melanogaster His3:CG33863 (100% identical), mouse H3c13 (100% identical), rat H2bc18 (100% identical), tropical clawed frog h3c14 (100% identical), zebrafish si:dkey-23a13.4 (100% identical). Paralogues in human: H3C13 (100% identical), H3C15 (100% identical), H3C1 (99% identical), H3C10 (99% identical), H3C11 (99% identical), H3C12 (99% identical), H3C2 (99% identical), H3C3 (99% identical), H3C4 (99% identical), H3C6 (99% identical), H3C7 (99% identical), H3C8 (99% identical), and 8 more.
Diseases named in the same sentence as H3C14 in open-access papers:
H3C14 is named in the same sentence as 6 diseases in open-access papers, as found by Europe PMC text mining. Sharing a sentence is not in itself a finding about the gene and the disease. The quoted sentences say what the papers report.
Bladder Cancer (1 paper, 2025). "Altogether, our study highlights the critical role of EV‐mediated histone dynamics in GCB resistance and identifies H3C14 and its trafficking pathways as actionable targets for overcoming chemoresistance in bladder cancer." (PMID 41159684, 2025). "Loss of H3C14 enhances GCB resistance, promotes malignant phenotypes, reduces apoptosis and alters the expression of key GCB‐metabolizing enzymes, highlighting its potential as a therapeutic target in GCB‐refractory bladder cancer." (PMID 41159684, 2025). "H3C14 modulates gemcitabine metabolism and is selectively excluded via extracellular vesicles (EVs) in gemcitabine (GCB)‐resistant bladder cancer." (PMID 41159684, 2025). "Collectively, these findings identify H3C14 as a critical modulator of GCB sensitivity and tumour aggressiveness in bladder cancer." (PMID 41159684, 2025). "Although Excretion‐EVs did not directly induce drug resistance in recipient bladder cancer cells, their selective enrichment in regulatory proteins, such as H3.2 (H3C14), LAMB1 and CD147, suggests an indirect role in maintaining chemoresistance." (PMID 41159684, 2025).
cancer (2 papers, 2022 to 2025). A tumor composed of atypical neoplastic, often pleomorphic cells that invade other tissues. "Notably, gain‐of‐function of H3C14 restores GCB sensitivity, whereas its loss promotes a more aggressive cancer phenotype and apoptosis resistance." (PMID 41159684, 2025). "On the other hand, in transcriptional misregulation in the cancer signaling pathway, only MYCN expression was notably decreased, and the expression of 20 genes, including GADD45A, CXCL8, JMJD1C, RUNX1, and H3C14, was significantly increased in NHEKs upon HPV8 E7 expression." (PMID 35665406, 2022).
tumor (2 papers, 2024 to 2025). "The identification of Excretion‐EVs as carriers of tumour‐suppressive proteins, such as H3.2 (H3C14), CD147 and LAMB1, highlights an underexplored mechanism of GCB resistance involving the active excretion of unwanted intracellular regulators via EV secretion." (PMID 41159684, 2025). "To assess the role of H3C14 in vivo, we established a subcutaneous xenograft tumour model using T24GCB‐Vector and T24GCB‐H3C14 cells in nude mice." (PMID 41159684, 2025). "This hypothesis is supported by our observation that H3C14 overexpression reduces both GCB resistance and tumour aggressiveness, suggesting that its excretion via Excretion‐EVs may represent an adaptive strategy of GCB‐resistant cells to maintain their survival and aggressiveness." (PMID 41159684, 2025).
H3C14 also shares sentences with these, for which no sentence is quoted: gastric cancer (2 papers); Bladder Urothelial Carcinoma (1); head and neck cancer (1).